IGF1 (insulin like growth factor 1)
Diseases named in the same sentence as IGF1 in open-access papers (continued):
Sharing a sentence is not in itself a finding about the gene and the disease.
Insulin resistance (continued). "Insulin resistance promotes the progression of UM mainly by enhanced expression of IGF-1, which is closely associated with scleral infiltration and systemic metastasis in UM." (PMID 36003786, 2022). "GH acts in part through induction of insulin-like growth factor 1 (IGF1), and excess GH/IGF1 signaling has been linked to pathologies such as insulin resistance, acromegaly, and cardiomyopathy." (PMID 35250583, 2022). "Insulin resistance, observed frequently in obese individuals, is associated with an early rise in insulin-like growth factor 1 (IGF-1) levels and IGF-1 receptors in WAT and other tissues." (PMID 35328822, 2022). "Maternal obesity and an energy-dense diet can cause an increase in insulin and IGF-1 serum levels, producing metabolic disorders, such as insulin resistance, GDM, and high birth weight (> 4,000 g) due to a higher level of body fat." (PMID 35813659, 2022). "Of note in this regard, a single human proband with a homozygous LoF mutation in IGF1 had elevated circulating GH and severe insulin resistance." (PMID 36530175, 2022). "The pathophysiological pathway of insulin resistance causing adrenal mass is less well characterized, although mechanisms for this pathway have been proposed, including the stimulation of IGF-1 and IGF-2 receptors." (PMID 35457158, 2022). "Studies have shown that insulin resistance in a child with IUGR is linked to higher IGF-1 and BMI levels during postnatal catch-up growth." (PMID 36714657, 2022). "In our previous study, the increased resorption had been associated with the onset of insulin resistance along with a higher degree of OC decarboxylation and a higher circulating IGF1." (PMID 35574450, 2022). "There is still not very clear about the precise underlying mechanisms of the correlation between IGF-1 and insulin resistance." (PMID 34485526, 2021). "Low IGF-1 concentrations are associated with several cardiometabolic risk factors including obesity, insulin resistance, diabetes and inflammation." (PMID 33816541, 2021). "IGF-1 deficiency is intimately linked to insulin resistance, and the associations we observe with low IGF-1 and elevated HbA1C are consistent with a key role for metabolic dysregulation in MDD, or at least certain subtypes thereof." (PMID 34234104, 2021). "Previous studies have shown that insulin resistance in acromegalic patients is multifactorial, with age, greater duration of the disease, higher BMI, and higher IGF-1 levels being primary risk factors." (PMID 33859902, 2021). "Acute and chronic sleep loss induces glucose intolerance and insulin resistance; decrease insulin-like growth factor (IGF)-1 and adiponectin levels; and induce dyslipidemia and systemic low-grade inflammation in non-obese subjects (humans and animal models)." (PMID 34539357, 2021). "Secondly, it is a cross-sectional study, so the causal relationship between IGF-1 and insulin resistance cannot be clarified." (PMID 34485526, 2021). "And further studies are needed to determine the characteristics of the pathophysiology of the association between IGF-1 and insulin resistance in obese children and obesity-related complications." (PMID 34485526, 2021). "Diabetes is a frequent complication of acromegaly and Cushing’s disease caused by insulin resistance and impaired insulin secretion as a result of excess GH/IGF-1 and cortisol production, respectively." (PMID 34275099, 2021). "Another possible explanation for the association between IGF-1 and insulin resistance is driven by chronic inflammatory." (PMID 34485526, 2021). "In the study, we confirmed a significant association between low levels of IGF-1 and insulin resistance in obese prepubertal boys." (PMID 34485526, 2021). "In conclusion, we have found a strong correlated relationship between low IGF-1 and insulin resistance in obese prepubertal boys independently of other risk factors." (PMID 34485526, 2021).
Insulin resistance (continued). "Proposed mechanisms of the relationship between IGF1 and the risk of diabetes include IGF1 has the homology structure with insulin and is similar to insulin function that regulates hormones for insulin resistance and subsequently regulates glucose homeostasis." (PMID 34201855, 2021). "Given that SOCS proteins inhibit insulin/IGF-1 signaling, they are able to elicit insulin resistance, a condition which is known to be associated with aging." (PMID 34476533, 2021). "Excess adiposity causes insulin resistance, which in turn leads to an elevated levels of bioactive insulin-like growth factor-1 (IGF-1); both insulin and IGF-1 can increase proliferation and reduce apoptosis in sensitive cells." (PMID 34051796, 2021). "Previous animal studies reported that serum and liver IGF-1 levels were decreased in fatty liver disease caused by insulin resistance, and NAFLD models with low IGF-I levels exhibited impaired muscle strength, function, and lower muscle fiber diameters." (PMID 33807573, 2021). "Higher insulin resistance and IGF-1 concentrations have, in turn, also been linked to a higher risk of breast cancer." (PMID 33669972, 2021). "Both pathological excess, as in acromegaly, and deficiency of IGF-1 are associated with glucose intolerance, insulin resistance and increased risk of type 2 diabetes and cardiovascular morbidity and mortality." (PMID 32548700, 2020). "A recent study further indicated that IGF1 status is associated with insulin resistance in young SMA patients with early-onset sarcopenia." (PMID 33339220, 2020). "In this study, we found that the association between genetically predicted serum IGF-1 levels and type 2 diabetes was partially attenuated after adjustment for fasting insulin levels or insulin resistance through multivariable MR analysis." (PMID 32548700, 2020). "Type 2 diabetes, insulin resistance, and high levels of IGF-1 have been linked to the increased risk of breast cancer." (PMID 32630445, 2020). "Indirectly, this theory is supported by dramatically reduced Insulin receptor transcripts and increased transcription of Insulin-like growth factor 1 (IGF-1) in CXCR5-deficient RPE cells suggestive of insulin resistance." (PMID 32492870, 2020). "Possibly, the associations depend on the influence of GH and IGF-1 on underlying risk factors and processes, such as hypertension, insulin resistance and inflammation, and oxidative stress." (PMID 32458292, 2020). "Genetically higher IGF-1 levels were additionally associated with some components of the metabolic syndrome, the most robust association being with fasting insulin and insulin resistance." (PMID 32548700, 2020). "Insulin resistance leads to increased levels of insulin and its associated growth factors, in particular insulin-like growth factor 1 (IGF-1), and the development of type 2 diabetes." (PMID 32630445, 2020). "Insulin resistance-associated factors, such as IGF1 and IGFALS, and inflammation-related factors, such as CSF1 and TGFβ2, were all highly enriched in the MetS group." (PMID 32133283, 2020). "It is also proposed that insulin resistance and insulin-like growth factor 1 (IGF-1) system play a critical role in the association between MetS and BC risk." (PMID 32391265, 2020). "Though the exact mechanism has not been defined, many studies have found a correlation between IGF-1 deficiency and the development of insulin resistance." (PMID 30744635, 2019). "The association with low IGF-1 is probably related to the insulin-like actions of IGF-1 that promote hypoglycemia, and the fact that IGF-1 suppresses secretion of GH, which itself causes insulin resistance." (PMID 31416218, 2019). "Hyperinsulinemia with a decrease in the serum level of IGF-1 binding protein and an increase in IGF-1 is most often caused by insulin resistance." (PMID 31440472, 2019). "IGF-1 promotes fatty acid transport in muscle and its inhibition causes severe consequences like insulin resistance and even diabetes." (PMID 31252598, 2019).
Insulin resistance (continued). "Previous studies have shown that IGF-1 levels were associated with cardiovascular complications such as insulin resistance, MSx, and also lipid concentrations." (PMID 31601230, 2019). "Obesity is associated with insulin resistance and consequently higher rates of circulating insulin leading to a higher bioactivity of Insulin-like-growth factor 1 (IGF-1)." (PMID 31052303, 2019). "The potential link of lifestyle factors to breast cancer risk or prognosis through IGF-1 signaling and the insulin resistance pathway has been suggested in several studies." (PMID 31816813, 2019). "Altered levels of GH and IGF-1 have been associated with insulin resistance and the development of diabetes mellitus." (PMID 30744635, 2019). "Hyperinsulinemia induces insulin resistance in tumor and is linked to lower the IGF-1 expression and aromatase activity resulting in poor prognosis." (PMID 31398937, 2019). "A condition known as insulin-resistance does exist in obese patients and is associated with high levels of insulin-like growth factor I (IGF1) and blood insulin." (PMID 31766196, 2019). "Central obesity and components of metabolic syndrome can result in visceral fat deposition that is associated with insulin resistance and high IGF1 levels, which can influence the carcinogenic processes." (PMID 30563254, 2018). "A low-serum level of IGF-1 has been associated with insulin resistance, and treatment with recombinant IGF-1 has been shown to improve insulin sensitivity and glucose metabolism." (PMID 29422987, 2017). "IGF-1, instead, enhances insulin metabolic and anabolic action, and lower IGF-1 levels have been shown to associate with impaired glucose tolerance, insulin resistance and metabolic syndrome, and to predict T2DM onset." (PMID 28881681, 2017). "Nowadays, increasing evidences suggest that a lower IGF-1 level is associated with obesity, insulin resistance, metabolic syndrome, impaired glucose tolerance, nonalcoholic fatty liver disease (NAFLD) and cardiovascular disease." (PMID 27343122, 2016). "A good example is the finding that low circulating levels of IGF-1 are independently associated with hyperglycaemia and insulin resistance in adults." (PMID 26733412, 2016). "IGF-1 promotes fatty acid transport in muscle and its inhibition causes severe consequences like insulin resistance and eventual diabetes." (PMID 26733412, 2016). "Accordingly, miR-190b is upregulated in tumor tissues, contributing to insulin resistance through downregulation of IGF-1, which is associated with poor prognosis." (PMID 27223464, 2016). "Low plasma IGF-1 is associated with reduced insulin sensitivity and increased insulin resistance, which had been showed in clinical studies." (PMID 27343122, 2016). "Peripheral insulin resistance augments IGF1 levels, and loss of imprinting (LOI) of the IGF2 gene is associated with poor survival in CRC." (PMID 27409167, 2016). "One recent large-scale community based Framingham Heart Study suggested that lower IGF-1 levels are associated with insulin resistance and MetS." (PMID 26467524, 2015). "The hyperphosphorylation is associated with brain insulin resistance that results from the impairment of several pathways such as insulin and IGF-1 signaling." (PMID 25755673, 2015). "Recent data support that IGF-1 deficiency increases insulin resistance, impairs lipid metabolism, promotes oxidative damage and deregulates the neuro-hormonal axis." (PMID 26467524, 2015). "Patients with type 2 diabetes mellitus are at an increased risk of cancer and they are characterized by insulin resistance with hyperinsulinemia and hyperactivity in IGF1 signaling." (PMID 25655946, 2015). "HFD was associated with insulin resistance, and elevated serum levels of insulin and IGF-1 were supposed to exert promotion of PCa development and progression." (PMID 25722971, 2015). "Excess GH causes insulin resistance and hyperglycemia, whereas IGF-1 has insulin-like effects that reduce blood glucose levels." (PMID 26514337, 2015).
Insulin resistance (continued). "IGF-1 circulating levels decrease with aging, and such a decrease is associated with insulin resistance and dyslipidemia." (PMID 26467524, 2015). "In Chr 12q23, variations near or within STAB2 are associated with coronary restenosis (P = 1.0 × 10-7), coronary disease (P = 1.0 × 10-5) and stroke (P = 5.4 × 10-4), and those near IGF1 are associated with insulin resistance (P = 2.0 × 10-9)." (PMID 25689165, 2015). "With regard to IGF1, a recent paper reported that higher IGF1levels were associated with more severe insulin resistance and hyperglycaemia." (PMID 24692509, 2014). "Dysregulation of the IGF pathway is implicated in the pathogenesis of HCC, particularly in patients with NAFLD and the metabolic syndrome, which are associated with insulin resistance, chronic hyperinsulinemia, and increased levels of bioavailable IGF-1." (PMID 25052889, 2014). "The pro-insulin factor, IGF-1 is known to confer insulin-like action to stimulate glucose uptake and its mal-regulation is recognized to associate with insulin resistance and diabetes." (PMID 24498028, 2014). "In accordance with these lines of evidence, low serum IGF-1 levels were associated with insulin resistance and poor prognosis in our HCC patients." (PMID 24586785, 2014). "The association of insulin resistance with IGF-1 concentrations seems to be U shaped in patients who did not undergo bariatric surgery and there is not enough data to make such an assumption for bariatric surgery patients." (PMID 24736741, 2014). "Nonalcoholic fatty liver disease (NAFLD) is known to be associated with insulin resistance, atherosclerosis, and low serum IGF1 levels." (PMID 25117570, 2014). "In conclusion, the involvement of insulin resistance in response to IGF-1 deficiency was further substantiated by this invitro evidence." (PMID 24586785, 2014). "Taken together, these results suggest that low serum IGF-1 level is associated with insulin resistance and poor overall survival in HCC patients." (PMID 24586785, 2014). "Obesity is associated with insulin resistance, which alters the levels of plasma glucose, insulin and insulin-like growth factor-1 (IGF-1)." (PMID 24396438, 2014). "Insulin resistance and hyperinsulinemia are also associated with downregulation of IGFBPs, increasing the levels of bioavailable IGF-1." (PMID 24280167, 2013). "The development of insulin resistance is linked to chronic inflammation and the production of adiponectin and IGF-1." (PMID 23819063, 2013). "Type 2 diabetes is associated with insulin resistance, compensatory hyper-insulinemia, and up-regulated level of IGF-1." (PMID 23472134, 2013). "Activation of NF-κB is a common characteristic of many tumors and is associated with insulin resistance and elevated circulating levels of leptin, insulin, or IGF-1." (PMID 24280167, 2013). "Hyperinsulinemia and/or hyperglycemia are hallmarks of the obese state and are associated with insulin resistance, aberrant glucose metabolism, chronic inflammation, and the production of other metabolic hormones such as IGF-1, leptin, and adiponectin." (PMID 23050968, 2012). "This suggests that, in addition to insulin resistance, AD is associated with IGF-1 resistance in the brain, and therefore attending to just one or the other signaling pathway will likely not be sufficient to arrest disease." (PMID 22329651, 2012). "IUGR causes fetal hypoglycemia, decreases postnatal growth, and predisposes to adult onset insulin resistance, both of which are modulated by IGF-1." (PMID 22548154, 2012). "On the other hand, adiponectin reduction is associated with insulin resistance which leads to an increase in the levels and activity of IGF1." (PMID 23213569, 2012). "Early menarche is also linked to hyperinsulinemia, insulin resistance, and high insulin-like growth factor 1 [IGF-1]." (PMID 21386133, 2011).
Insulin resistance (continued). "Epidemiologic studies have shown that higher serum levels of insulin and insulin resistance are associated with an increased risk of PC, even after adjustment for BMI, body fat, levels of sex hormone, and insulin-like growth factor 1 (IGF-1)." (PMID 22110984, 2011). "From earlier studies it is known that obesity, low levels of IGFBP-1 and an increased IGF-1:IGFBP-1 ratio are factors associated with insulin resistance in men and women." (PMID 17212815, 2007). "A trend towards significance of association between insulin resistance/sensitivity and IGF-1 levels was seen." (PMID 17953765, 2007). "Various associations between IGF-1 and insulin resistance/sensitivity shall be determined by suitable statistical methods." (PMID 17953765, 2007). "In addition, the low-grade inflammation associated with obesity causes metabolic changes such as insulin resistance, which leads to increased circulating insulin and IGF-1 levels." (PMID 40496310, 2025). "These research findings suggest that treatment strategies targeting IGF-1 as a central focus may serve as a powerful and effective therapy for addressing mitochondrial dysfunction caused by insulin resistance." (PMID 40927684, 2025). "Several animal studies reported that long-term caffeine intake is inversely associated with insulin resistance through various mechanisms, including improved insulin/IGF-1 signaling via the induction of insulin receptor substrate 2 or a decrease in circulating catecholamines." (PMID 40362793, 2025). "Across the UK Biobank, All of Us, and BioMe, risk variants and genes had simultaneous positive associations with liver enzymes, insulin resistance markers (HbA1c, IGF-1, and TyG index), serum lipids, and physical measurements, whereas protective variants and genes had the inverse." (PMID 40065360, 2025). "Similarly, IGF-1, the mediator of GH, has also been reported to be associated with insulin resistance, even at low levels." (PMID 39611962, 2025). "It further reduces IL-8 expression and modulates pathways associated with inflammation, UV-induced mutagenesis, and insulin resistance by targeting insulin-like growth factor-1 (IGF-1) and tumor necrosis factor alpha (TNF-α), particularly relevant to colorectal cancer." (PMID 40909085, 2025). "In addition, obesity-induced insulin resistance is associated with an increase in insulin-like growth factor 1 (IGF-1), which leads to the activation of AKT/mTOR/PI3K or ERK/RAS/MAPK pathways promoting the development of TC." (PMID 41301715, 2025). "Hyperinsulinemia, a hallmark of insulin resistance in T2D, results in sustained activation of insulin receptors—particularly the mitogenic insulin receptor isoform A—and increases circulating levels of insulin-like growth factor 1 (IGF-1)." (PMID 41008833, 2025). "Previous studies have shown that elevated IGF-1 activity may lead to chronic anovulation, insulin resistance, and increased adrenal androgen secretion, causing PCOS-like symptoms." (PMID 41367917, 2025). "Additionally, IGF-1 loss, insulin resistance, stroke risk, and cortisol levels all contribute to disease susceptibility." (PMID 40884186, 2025). "The IGF-1 signaling pathway regulates mitochondrial morphology and function by participating in mitochondrial fission and cellular renewal processes, thereby influencing cellular tolerance to damage associated with insulin resistance." (PMID 40927684, 2025). "Also, low IGF-1 levels were associated with insulin resistance, and restoration of IGF-1 levels had a positive effect on IGF-1 signaling." (PMID 41153350, 2025). "However, GH administration in non‐GHD populations is associated with several risks, including insulin resistance, dyslipidemia, cardiomyopathy, hypertension, and potentially tumor development due to GH/IGF‐1 signaling." (PMID 41089172, 2025).